CRP (C-reactive protein)
Diseases named in the same sentence as CRP in open-access papers (continued):
Sharing a sentence is not in itself a finding about the gene and the disease.
unstable angina (continued). "Prognostic value of serum Cp has been compared against that of CRP and fibrinogen in 40 patients of unstable angina over 12 months period." (PMID 24049653, 2012). "According to this finding, we decided to conduct this study to assess the relationship between CRP and complex lesions of coronary arteries in patients with unstable angina." (PMID 22577410, 2010). "According to our findings, there is a significant difference considering CRP level in unstable angina patients who have complex lesions compared with simples ones." (PMID 22577410, 2010). "A previous study found increased plasma IL-12 concentrations in patients with CAD, and a significant increase in plasma IL-12 levels was found in patient with unstable angina and stable angina, especially in the unstable angina group; the plasma hs-CRP level was positively correlated with IL-1213." (PMID 40303485, 2025). "Moreover, patients with stable angina who received boron supplementation experienced a decrease in C-reactive protein (CRP), low-density lipoprotein (LDL), and total cholesterol levels, along with an improvement in high-density lipoprotein (HDL) levels." (PMID 38700634, 2025). "Similar results were observed when stratifying by DR severity, where the trend test suggested statistically significant differences in age, gender, race, high C-reactive protein level, walking difficulty, history of congestive heart failure, angina, and comorbid ocular diseases." (PMID 38714673, 2024). "The study on the treatment of angina revealed that THSWD effectively reduced the levels of high-sensitivity C-reactive protein (hs-CRP), triglycerides (TG), total cholesterol (TC), and low-density lipoprotein cholesterol (LDL-C) in serum, when compared to the group that did not use THSWD." (PMID 38902693, 2024). "In addition, elevated levels of CRP are predictive in some cardiac diseases like unstable angina and myocardial infarction." (PMID 38316807, 2024). "However, we observed a higher need for revascularization and angina outcomes in the group with high hs-CRP compared to low hs-CRP." (PMID 37273333, 2023). "CRP is known to be a strong independent risk factor for cardiovascular events, not only among those with stable and unstable angina but also among individuals with no current evidence of cardiovascular disease." (PMID 36042900, 2022). "According to one Taiwanese study, the serum CRP levels were remarkably higher in subjects with AMI onset < 6 h than in individuals with stable angina (2.7 ± 2.3 mg/L vs. 1.4 ± 0.7 mg/L, p < 0.001) and in control individuals (2.7 ± 2.3 mg/L vs. 1.0 ± 0.6 mg/L, p < 0.001)." (PMID 36579565, 2022). "In patients with unstable angina, we discovered that activation of immune-inflammatory pathways (CRP and cytokines including IL-6) affects the physio-affective phenome of unstable angina, and that these effects are mediated by increased atherogenicity and insulin resistance." (PMID 36011997, 2022). "In addition, low to moderate increases in CRP predict subsequent cardiovascular events, often occurring years later, in patients with angina and in healthy individuals." (PMID 34945133, 2021). "Through the meta-analysis of CRP and the frequency of angina pectoris, we believe that the reason for the high heterogeneity may be due to the different measurement units used in the two outcome indicators in each study." (PMID 34335841, 2021). "Therefore, subgroup analysis of CRP and frequency of angina pectoris is performed according to the different measurement units." (PMID 34335841, 2021). "Moreover, family history of CHD and C-reactive protein level between controls with stable and unstable angina patients were highly significant (P < 0.001)." (PMID 32351734, 2020). "Increased CRP at admission in patients with unstable angina or non-ST-segment myocardial infarction is associated with increased 14-day mortality, even in patients with a negative rapid cardiac troponin test." (PMID 33094574, 2020).
unstable angina (continued). "Comparison of the serum hs-CRP and Gensini score between stable angina and unstable angina groups." (PMID 31934638, 2019). "Previous studies have also shown that neopterin, but not CRP, is associated with LV dysfunction and predicts an increased cardiovascular risk in patients with stable angina pectoris." (PMID 31861167, 2019). "HCY was transferred into binary variable according to the cutoff point of 17.55 μmol/L, then HCY ≥17.55 μmol/L and < 17.55 μmol/L as a binary variable, together with preinfarct angina, CRP and NLR were tested by multiple logistic regression to decide the independent predictors of SR." (PMID 29940881, 2018). "CRP levels might be a valid prognostic marker for differentiation between patients with unstable angina and chronic stable angina; however, they fail to differentiate patients with stable CAD from patients with acute coronary syndrome." (PMID 30344267, 2018). "In a follow-up study of patients with stable angina a number of adhesion molecules were measured at baseline, but only VCAM independently predicted risk of death from IHD adding to the risk prediction from the classical risk factors and C-reactive protein." (PMID 26298350, 2015). "While single-marker CRP models showed strong associations with angina, MI, and CHD, those results were no longer significant when controlling for triglycerides and glycohemoglobin." (PMID 25788869, 2015). "One explanation for similar CRP expression between cases and controls might be that all study subjects had been diagnosed with stable angina pectoris." (PMID 15482602, 2004). "In addition, high serum CRP level was associated with the presence but not the degree of CAD in patients with stable angina." (PMID 38398769, 2024). "CRP and OxLDL are important activators of the classical pathway and it has been demonstrated that quantities of these proteins are significantly or tend to be larger in patients with unstable angina and AMI than in those with stable angina according to histological and serological studies." (PMID 35085285, 2022). "Moreover, of the patients presenting elevated levels of C reactive protein, 9 of these had recurrent angina events or restenosis (1.27 mg/dl [0.27-2.3 mg/dl] in patients with recurrent events vs. 0.43 mg/dl, [0.01 - 0.8 mg/dl] in patients without events at 6 months, p =0.029)." (PMID 25253465, 2014). "After treatment, the treatment group showed greater improvements in angina frequency, blood lipid profiles (lower TC, LDL, higher HDL), and reduced CRP and BNP levels compared to the control group (P < .05), with a higher total effective rate (P < .05)." (PMID 40258733, 2025). "We also assessed nitroglycerin reduction dose, angina pectoris frequency, Seattle angina pectoris score (SAQ), quality of life (SF-36), TCM syndrome score, ECG changes, blood lipids, serum hypersensitive C-reactive protein and intestinal flora changes." (PMID 36388277, 2022). "In a study population similar to our study (coronary patients with stable angina), the authors could find that in gender female the higher platelet reactivity while on DAPT with clopidogrel was associated with a pro-inflammatory profile, with higher levels of C-reactive protein and leukocytes." (PMID 31774869, 2019). "The highest apoCIII, hs-CRP and TNF-α levels were detected in the CHD patient subgroups with AMI, followed by those with unstable angina and then those with stable angina." (PMID 30053815, 2018). "There is also a significantly positive correlation between plasma concentrations of NAMPT and high sensitivity C-reactive protein (hs-CRP) and IL-6 in the patients with stable angina pectoris." (PMID 26389889, 2015). "Comparisons of differing association between the two endpoints showed significant/marginally significant differences in the relationships between the inflammatory biomarkers (CRP, IL-6, fibrinogen), fibrin D-dimer and MI/CHD death and uncomplicated angina." (PMID 19682232, 2009).
unstable angina (continued). "In patients with typical angina pectoris without CAD, increased CRP levels were associated with an impaired myocardial perfusion reserve index following stimulation with intravenous adenosine and intracoronary acetylcholine in cardiac magnetic resonance." (PMID 38398769, 2024). "Furthermore, we found that CRP, TG, and LDL-C were independent predictors of cardiovascular events in patients with stable angina, while HDL-C was a protective factor." (PMID 39507388, 2024). "Moreover, CRP, TC, TG, and LDL-C were positively correlated with the severity of angina, while HDL-C was negatively correlated." (PMID 39507388, 2024). "Moreover, the stable angina and STEMI patients with the CC genotype had significantly elevated high-sensitivity C-reactive protein levels than those with the GG genotype." (PMID 38250610, 2024). "What is more, high-sensitivity C-reactive protein (CRP) is inversely related to coronary flow reserve in patients with angina and without obstructive CAD, showing a direct relationship between inflammation and CMVD." (PMID 35983182, 2022). "In a meta-analysis of TACTICS-TIMI 18, elevated WBC and C-reactive protein (CRP) at the time of unstable angina/non-ST elevation myocardial infarction (UA/NSTEMI) presentation correlated with higher 6-month mortality." (PMID 33078375, 2021). "Indeed, serum CRP level is reported to be a powerful predictor of ischemic CVD events in apparently healthy subjects, as well as in patients with stable or unstable angina." (PMID 33621259, 2021). "Unstable angina or non-ST-elevation myocardial infarction patients with increased hs-CRP level were randomly assigned to atorvastatin-based standard medical therapy or standard therapy plus STS injection (80 mg, once daily for 14 consecutive days)." (PMID 29234038, 2017). "Elevated CRP levels have not been shown to correlate with significantly worsened outcomes in patients with stable angina, however." (PMID 22708908, 2012). "In terms of the association of CRP and ACS it is important to distinguish cases without (unstable angina) and with necrosis (acute MI)." (PMID 21150016, 2010). "In this study, we aimed to compare the levels of inflammatory factors (CRP, PCT) and blood lipids (TC, TG, HDL-C, LDL-C) between patients with stable angina and control group, and to explore the correlation between these parameters and the severity and prognosis of stable angina." (PMID 39507388, 2024). "In addition, the stable angina group had significantly higher fasting sugar, HbA1C, total cholesterol, triglyceride, LDL-C, uric acid, BUN, creatinine, total WBC/neutrophil/monocyte/lymphocyte counts, and hs-CRP, and lower HDL-C, eGFR, and hemoglobin than the control group." (PMID 38250610, 2024). "A retrospective clinical study found that unstable angina patients treated with statins for at least 1 month had fewer CD4+CD28null T cells than those given standard anti-ischemic therapy without statins, an effect that correlated well with plasma C-reactive protein (CRP) levels." (PMID 38963798, 2024).
respiratory failure (170 papers, 2004 to 2026). The significant impairment of gas exchange within the lungs resulting in hypoxia, hypercarbia, or both, to the extent that organ tissue perfusion is severely compromised. "Elevated C-reactive protein (CRP ≥ 10 mg/dL) was also strongly associated with acute respiratory failure (HR: 2.743, 95% CI: 2.437–3.087), emphasizing the contribution of systemic inflammation." (PMID 40723190, 2025). "Recent studies showed that COVID‐19 patients with elevated levels of HBP, IL‐6, and CRP faced a significantly increased risk of respiratory failure." (PMID 39187469, 2024). "An association between elevated interleukin 6 (IL-6) and C-reactive protein (CRP) after this initial period of viral replication was soon correlated with risk of respiratory failure and mechanical ventilation." (PMID 39220656, 2024). "Multivariable logistic regression revealed vaginal delivery, respiratory failure, co-infection with a virus, C-reactive protein (CRP) > 8 mg/L as significant risk factors for MRSA infection." (PMID 39483528, 2024). "Multivariable logistic regression analysis revealed that vaginal delivery (P = 0.010), respiratory failure (P = 0.006), co-infection with a virus (P = 0.004) and CRP > 8 mg/L (P = 0.005) remained independent risk factors for acquiring MRSA infection." (PMID 39483528, 2024). "The results suggested that NYHA class IV, type II respiratory failure, acid-base imbalance, CRP, and D-dimer were associated with death in patients with cor pulmonale." (PMID 37400818, 2023). "Higher INR, elevated CRP, increased heart rate and more severe respiratory failure are risk factors for occurrence of AF in critical illness, suggesting an association between cardiac, respiratory and immune and coagulation pathways." (PMID 37780563, 2023). "The mediation analysis confirmed that CRP, neutrophils, lymphocytes, and age are linked with P/F in the same pathogenetic chain leading to respiratory failure." (PMID 37373750, 2023). "In conclusion, NYHA class IV, type II respiratory failure, acid-base imbalance, CRP, and D-dimer were risk factors for death in patients with cor pulmonale living at high altitudes." (PMID 37400818, 2023). "The univariate Cox proportional hazards analysis showed that HYHA, respiratory failure, cardiac injury, acute renal insufficiency, electrolyte acid-base balance disorder, C-reactive protein, D-dimer, and PA diameter were associated with death." (PMID 37400818, 2023). "In this study, NYHA class IV, type II respiratory failure, acid-base imbalance, CRP, and D-dimer were risk factors for death in patients with cor pulmonale living at high altitudes." (PMID 37400818, 2023). "Recent studies have also found a link between high CRP levels and respiratory failure, with a higher risk of AKI, VTE, and ARDS necessitating mechanical ventilation." (PMID 37108026, 2023). "Higher CRP levels are associated with unfavorable features of COVID-19 diseases, such as respiratory failure, acute heart injury, and fatality." (PMID 37551398, 2022). "Respiratory failure was associated with renal replacement therapies (OR 13.8, 95% CI 1.3–143.9, p = 0.006), postoperative creatinine (md 0.27 mg·dL−1, 95% CI 0.1–0.4, p = 0.001), and C-reactive protein (md 33.5 mcg·L−1, 95% CI 0.1–66.8, p = 0.049)." (PMID 40218105, 2025). "In our study, it was seen that the variables that best predicted the development of severe respiratory failure were the presence of underlying diseases, age, neutrophil and lymphocyte counts, the CT score of the upper lung zone, and serum CRP and procalcitonin levels." (PMID 39685844, 2024). "Some studies have already identified an association between CRP and respiratory failure." (PMID 37373750, 2023). "Moreover, CRP concentration higher than 32.5 mg/L showed high rates of sensitivity to detect patients at risk for respiratory failure." (PMID 35052182, 2021).
respiratory failure (continued). "Underlying disease and initial CRP level were the two independent predictors of death; age, initial CRP level, and worst chest radiographic finding were the three independent factors predicting respiratory failure for adult SARS patients." (PMID 15200814, 2004). "Respiratory failure was associated with postoperative renal replacement therapies (OR 13.8, 95% CI 1.3–143.9, p = 0.006) and with higher postoperative values of creatinine (md 0.27 mg·dL−1, 95% CI 0.1–0.4, p = 0.001) and C-reactive protein (md 33.5 mcg·L−1, 95% CI 0.1–66.8, p = 0.049)." (PMID 40218105, 2025). "Additionally, immunological and biochemical variables such as the total number of neutrophils and lymphocytes, interleukin-6 (IL-6), C reactive protein (CRP), lactate dehydrogenase, d-dimers or ferritin levels have been associated with respiratory failure and death." (PMID 35547738, 2022). "The significant up-regulated IL-6 and CRP level were observed in severe influenza (especially H1N1category) and were linked to severe tissue and organ damage and to the likelihood of developing more severe clinical manifestations, respiratory failure and complications, as well as poorer outcome." (PMID 33537328, 2020). "However, by using the logistic regression model for multivariate analysis, severe underlying disease and high initial CRP level were the only two factors that predicted death; age, initial CRP level, and worst chest radiographic findings predicted respiratory failure." (PMID 15200814, 2004). "Elevated CRP levels correlate with unfavorable outcomes, including accelerated disability in MS, IL-6-mediated astrocyte injury in NMOSD, respiratory failure in GBS, and crisis susceptibility in MG." (PMID 41683748, 2026). "Similar results were observed in an Italian study, which confirmed that CT involvement correlates with CRP, IL-6, IL-8, and tumor necrosis factor α (TNF-α) serum levels in severely ill patients with a high risk of acute respiratory failure." (PMID 40428781, 2025). "Both NLR and PLR demonstrated a strong correlation with acute respiratory failure and complications, like CRP, but with key differences in their potential applications." (PMID 40282925, 2025). "Tocilizumab, an IL-6 receptor blocker, is a clinically established therapy that demonstrably improves outcomes in hospitalized patients with rapidly progressing respiratory failure and elevated inflammatory markers such as C-reactive protein (CRP)." (PMID 41176818, 2025). "Significant disparities in age, comorbidities like respiratory failure, C-reactive protein, lymphocyte count, red blood cell distribution width (RDW), SCI, procalcitonin (PCT), and D-dimer were depicted between the cd-COPD and non-cd-COPD groups." (PMID 40028201, 2025). "Although inflammatory markers are normally elevated intraoperatively and decrease during the first postoperative day, C-reactive protein values in the immediate postoperative period were significantly higher in patients who suffered respiratory failure." (PMID 40218105, 2025). "Preoperative oxygenation index (OI), body mass index (BMI), and biomarkers such as C-reactive protein (CRP) and D-dimer have been implicated as potential predictors in other forms of respiratory failure." (PMID 39898254, 2025). "Patients with vaginal delivery, respiratory failure, co-infection with a virus, and CRP > 8 mg/L were significantly more likely to develop MRSA infection than MSSA infection." (PMID 39483528, 2024). "Key predictors included low gestational age, low birth weight, high results of C-reactive protein and white blood cell counts, and tachycardia and respiratory failure." (PMID 39408019, 2024). "The mSCOPE score consists of three different laboratory test variables (ferritin, D-dimers, and CRP) and has been shown useful in predicting progression to respiratory failure or death among patients admitted to the hospital due to COVID-19 pneumonia." (PMID 37109014, 2023).